TNF (tumor necrosis factor)
Diseases named in the same sentence as TNF in open-access papers (continued):
Sharing a sentence is not in itself a finding about the gene and the disease.
tumor (continued). "As has previously been shown, Tim‐3‐ and PD‐1‐expressing exhausted CD8+ T cells in chronic viral infections and tumor microenvironments are dysfunctional, as indicated by their loss of IFN‐γ and TNF‐α." (PMID 26750587, 2016). "LCH cells, like tumor cells, release certain cytokines including Tumor Necrosis Factor (TNF)- α and Interleukin-117,18 that stimulate osteoclast activity leading to fragility of bone and increased fracture risk." (PMID 27413525, 2016). "Selected compounds were then characterized using cytotoxicity assays in which a cytokine-resistant human tumor cell line was sensitized to either TNF or lymphotoxin-α (LT-α)." (PMID 27617834, 2016). "This strategy has resulted in several tumor vascular ligands fused to TNFα for cancer therapy research, and even clinical trials are underway." (PMID 27342639, 2016). "MDSCs were isolated from the spleens of hTNF KI tumor-bearing mice undergoing treatment with anti-TNF blockers or with PBS, as control." (PMID 27148266, 2016). "Intriguingly, deletion of TNFα accelerates tumor development, which shows divergent roles of TNFα and TNFR1 in hepatocarcinogenesis." (PMID 27556180, 2016). "More importantly, combination therapy of TCP-1/TNFα and TCP-1/IFNγ synergistically suppressed tumor growth and alleviated systematic toxicity associated with untargeted therapy." (PMID 27342639, 2016). "RT in combination with ICB has been shown to reduce tumor-associated MDSCs in comparison to single therapy via the activity of CD8+ T cells and tumor necrosis factor (TNF) signaling in vivo." (PMID 27774435, 2016). "It was observed that the nanoconjugates preferentially accumulated in the tumor vasculature and suppressed the tumor mass more effectively as compared to the free tumor-necrosis factor." (PMID 27898016, 2016). "In this respect, NF-κB provides a mechanistic link between inflammation and cancer, whereas other factors such as TNF-a and IL-6–induced signaling have been recently shown to promote tumor growth in colitic carcinogenesis." (PMID 26716648, 2016). "Lastly, we studied natural killer (NK) cell function and found that tumor-infiltrating NK cells from mice fed the KD produce significantly more IFNγ and TNF in response to GL261-Luc2 cells than the cells isolated from SD fed animals." (PMID 27178315, 2016). "The antiproliferative and proapoptotic properties of IFN-γ and TNF-α, produced by activated T cells and monocyte-macrophages, are well established in many tumor models." (PMID 27882334, 2016). "Target: TNF-alpha inhibitor.Mechanism of action:Increases tumor cell apoptosis:–Enhancing IL-10Induces G0-G1 cell cycle arrest:–CDK2 inhibition.T- cells activated via B7 pathway:–Tyrosine phosphorylation of CD28." (PMID 27119356, 2016). "Most likely this first effector phase includes the secretion of TNFα which facilitates hemorrhage in the tumor, and the formation of large necrotic regions providing ideal conditions for the influx and proliferation of bacteria in the same phase." (PMID 26981777, 2016). "The activation of NFκB was further increased following radiation and constitution of macrophage-enriched tumor microenvironment, but was inhibited by blockade of TNF-α signaling." (PMID 26799286, 2016). "We analyzed the serum levels of cytokines IL-6, IL-8, IL-10, IFN-γ, and TNF-α in tumor-bearing mice." (PMID 27764779, 2016). "Because CDDO-Me enhanced LPS-induced TNF-α secretion, which is associated with M1 activation, we investigated the effect of CDDO-Me on the expression of IL-10 and VEGF, which are tumor-promoting factors produced by TAMs." (PMID 26918785, 2016). "The expression of TNF-α and Hes1 (a downstream effector of Notch signaling) in tumor tissue was higher than both normal muscle and atrophic muscle, while the expression of Klotho [an anti-inflammatory factor] was lower." (PMID 27378829, 2016).
tumor (continued). "Once a cell-mediated immune response is propagated, cytokines (IFN- γ and TNF-α) and chemokines along with contact-mediated cytotoxicity result in death of the tumor cells." (PMID 27782834, 2016). "Members of the Inhibitor of APoptosis (IAP) protein family suppress apoptosis within tumor cells, particularly in the context of immune cell-mediated killing by the tumor necrosis factor (TNF) superfamily cytokines." (PMID 27617834, 2016). "These tumor-infiltrating, antigen-specific T cells produce multiple cytokines (particularly high amounts of IFNγ and TNFα), exert cytotoxic activity, and improve the Teff:Treg ratio to delay tumor growth." (PMID 26910562, 2016). "TNF-α and IL-6 produced by the immune infiltrate and tumor cells are also considered as master switches between inflammation and cancer sustaining cellular transformation, survival, proliferation, angiogenesis, and metastasis." (PMID 27886105, 2016). "Strikingly, we demonstrated that BV6 enhances TNFα function in the induction of tumor cell apoptosis and necroptosis." (PMID 27014915, 2016). "Among various cytokines, TNFα affects many functions such as inflammation, tumor promotion, and anti-microbial immunity." (PMID 27386246, 2016). "Several proinflammatory cytokines, such as interleukin-1 (IL-1), IL-6, and TNF-a, expressed by the tumor environment induce CRP synthesis from the liver and other tissues." (PMID 26880857, 2016). "Previous studies elucidated that both NF-κB and TNF-α played important roles in connecting inflammation to tumor progression." (PMID 27356745, 2016). "TNF-α can also upregulate the expression of vascular endothelial growth factor and MMPs and activate survival signaling pathways, thus promoting tumor development and angiogenesis." (PMID 27658781, 2016). "High dose of TNFα mainly inhibits tumor angiogenesis, leading to vessel destruction which decreases the blood flow and oxygen required for the progression of tumor growth." (PMID 27342639, 2016). "To this end, we compared the effects of anti-TNF therapy on tumor growth using humanized knock-in mice, which produce human TNF instead of murine TNF (further referred to as hTNF KI mice)." (PMID 27148266, 2016). "Mouse models of colitis-associated colorectal cancer (CRC) and skin cancer show that blocking of TNF-α can prevent tumor formation." (PMID 28536374, 2016). "Intracellular production of IL-2, TNF and IFNγ by tumor-specific T cells was examined after overnight stimulation with MCC peptide." (PMID 27121060, 2016). "Combination of anti-TNF-α treatments with chemotherapy partly overcame chemoresistance of PDAC tumor cells and prolonged the survival of PDAC mouse model." (PMID 27835602, 2016). "Altogether, these data inform the SAR for our SMAC mimetics with respect to cIAP1 and cIAP2, suggesting that these IAP family members play an important role in tumor cell resistance to cytotoxicity mediated by TNF and LT-α." (PMID 27617834, 2016). "The stimulation of MSCs by IFN-γ and TNF-α released from activated tumor infiltrating T cells is likely responsible for the production of many factors that characterize the tumor microenvironment." (PMID 27211104, 2016). "The TNF-α expression was significantly positively correlated only with the presence of calcification in the tumours indicating that TNF-α is likely to participate in the development of calcification in the tumours." (PMID 26881177, 2016). "TNF-α is the key player in cancer-related inflammation, which can promote carcinogenesis, tumour growth, invasion, angiogenesis and epidermal-mesenchymal transition (EMT)." (PMID 27009073, 2016). "Most tumor-promoting cytokines, such as TNF-α and IL-6 are produced by lamina propria macrophages and dendritic cells (DC) during early states of CRC development." (PMID 27679575, 2016).
tumor (continued). "Further, in the existing study, expression of TNF-α was localized in the cytoplasm and was found to be significantly higher in the primary tumours of PTC patients than that observed in patients with benign thyroid diseases." (PMID 26881177, 2016). "In CRC, malignant cell derived TNF-α, enhances the growth and metastasis of the tumor as evidenced from animal models." (PMID 26896068, 2016). "CTLs use various mechanisms to kill tumor cells through granzymes, perforin, and ligands of the tumor necrosis factor (TNF) superfamily such as Fas ligand." (PMID 27686848, 2016). "In this study, individuals with orogastric cancer also showed elevated levels of TNF-α, showing a close relationship with this type of tumor." (PMID 26905729, 2016). "In this study, we employed a unique experimental model to study the effects of TNF neutralization on tumor-induced expansion of MDSCs in vivo." (PMID 27148266, 2016). "This suggested that PGN promoted the secretion of TNFα by tumors following irradiation and that TNFα plays a role in radiation-induced inhibition of tumor growth." (PMID 27708223, 2016). "In contrast, M1-like macrophages elicit cytotoxic responses from CD8+ T cells, through the secretion of IL-12, IL-18, type I IFNs, and tumor necrosis factor α (TNFα), and can directly kill tumor cells through the release of nitric oxide (NO)." (PMID 28003813, 2016). "Induction of EMT by tumor necrosis factor-α or Slug in HCT116 cells resulted in the dependence of tumor growth on ARHGEF5." (PMID 27617642, 2016). "To study the mechanism underlying this effect of the C-terminal domain, we analyzed expression of the cytokines, VEGF-A, interleukin 6 (IL-6), and tumor necrosis factor alpha (TNF-α), key genes for tumor growth, by RT-PCR." (PMID 28008951, 2016). "Compared with control, infusion of TNF-α stimulated the inflammatory tumor microenvironment of PDAC." (PMID 27835602, 2016). "The results indicated that TNF-α can increase the lymph node metastasis of orthotopic xenograft tumours in nude mice, and this effect was impaired when CCR7 was silenced." (PMID 27009073, 2016). "High levels of cytokines, including transforming growth factor beta (TGF-β), IL-6, IL-1 and TNF-α were produced during MM development in an in vivo mouse model by the MM cells and/or tumor infiltrating leukocytes." (PMID 27171110, 2016). "There is also the effect mediated by IL-1, IL-6, IFNγ and TNFα, that increases the invasiveness of the tumor on bone tissue." (PMID 27821086, 2016). "DEN-induced tumor related inflammation was further promoted through increased protein concentrations of liver IL-6 and TNF-α as compared to WT during carcinogenesis initiation." (PMID 27494874, 2016). "IFN-γ and TNF-α, which are cytokines produced and secreted by inflammatory cells in the tumour microenvironment, are major stimulators of PD-L1 expression in tumour cells." (PMID 27147225, 2016). "Observed during CRC tumorigenesis is loss of post-transcriptional regulation of tumor-promoting genes such as COX-2, TNFα and VEGF." (PMID 27677075, 2016). "It has been shown that tumor vascular-targeted delivery of TNFα is capable of increasing tumor concentration of TNFα and directing TNFα specifically to the tumor site." (PMID 27342639, 2016). "Tumor necrosis factor α (TNF-α), in addition to being cytotoxic for certain tumor cells, has turned out to be a pro-inflammatory cytokine that is involved in the regulation of immunity and several inflammatory diseases in humans and animals including horses." (PMID 27316332, 2016). "In this study, we identified decreased FSTL1 expression in NPC tissue sections, concomitant with downregulation of IL-1β and TNF-α in tumor tissue macrophages." (PMID 26918942, 2016). "Tumor necrosis factor-alpha (TNF) is a cytokine secreted by RCC with a number of tumor promoting properties and inhibition or blockade of TNF has shown clinical benefit in some patients with RCC." (PMID 26992212, 2016).
tumor (continued). "Consistently, we detected the expressions of CCR2 and TNFα on hepatic F4/80+ macrophages were markedly lower than that from tumour." (PMID 27270308, 2016). "A recent study found that engineered TNFα-expressing tumor cells target towards malignant cells and release TNFα locally to shrink the tumours." (PMID 27548121, 2016). "The existence of TNF-α secreted in autocrine or paracrine manner by components of tumor microenvironment highlights the significance of TNF-α in inflammation-associated tumor metastasis." (PMID 27556690, 2016). "Thirdly, involves activation of the cell's extrinsic apoptotic pathway by autocrine TNFα stimulation or the presence of TNF or TRAIL in the tumor microenvironment." (PMID 27223062, 2016). "Given the recent successes of immune modulators in cancer therapy and the improved understanding of immune evasion by tumours, we sought to determine the carcinogenic impact of chronic TNF-α and IL-1β exposure in a normal bronchial epithelial cell line model." (PMID 26759080, 2016). "It has been suggested that TANs from early tumors are more cytotoxic toward tumor cells and produce higher levels of TNF-α, NO, and H2O2 and, in established tumors, these functions are downregulated and TAN acquire a more protumorigenic phenotype." (PMID 26966341, 2016). "NK cells incubated with statins cannot hit tumor cells through perforin and granzyme pathways, even if FasL- and TNF-α-mediated killing is still conserved." (PMID 27834810, 2016). "Viability of both mPSCs and hPSCs was inhibited by anti-TNF-α treatment in comparable rates with PDAC tumor cells." (PMID 27835602, 2016). "In tumor-bearing mice, IL-2, IL-6, IL-12, TNF-α, and MCP-1 were up-regulated while IL-10 was down-regulated after cGAMP treatment." (PMID 26754564, 2016). "TNF-α in the tumor microenvironment further stimulates the production of other cytokines and chemokines." (PMID 27835602, 2016). "Nonetheless, during antitumor immune responses, NK cells can represent a source of IFN-γ, which potentially promotes the adaptive immune resistance of tumor cells, and TNF-α, a known EMT inducer." (PMID 27294158, 2016). "Upregulation of inflammatory cytokines (e.g., IL-6 and TNF-α) in livers with chronic injury is known to support tumor-promoting microenvironments." (PMID 26821924, 2016). "Immune cells that infiltrate the tumour, excluding NK cells, produce tumour cytokine promoters, such as tumour necrosis factor alpha [TNF-α] and interleukins IL-1β, IL-6, and IL-8, which increase signalling in pre-malignant cells." (PMID 26913068, 2016). "Ma-Mel-63a cells expressed and efficiently presented the Melan-A/MART-126-35 tumor epitope, as revealed by TNF-α-release assays." (PMID 27143649, 2016). "Constitutive production of TNF-α from the tumour microenvironment is a feature of many malignant tumours and its presence is associated with poor prognosis." (PMID 26881177, 2016). "In vivo, anti-TNF-α treatments showed effects in reducing desmoplasia and the tumor promoting inflammatory microenvironment in PDAC." (PMID 27835602, 2016). "In tumor tissue, the expression of TNF-α and IL-6 was increased both in control mice and HAI-1-deficient mice." (PMID 27612426, 2016). "When visible tumor appeared, the mice were injected with empty pRK5 plasmids or recombinant pRK5-A20 plasmids, as well as TNF-α." (PMID 26909601, 2016). "The TGF-β1 and TNF-α expression levels of the tumor tissues were determined via the Western blot method." (PMID 27881109, 2016). "TNF was initially described due to its potent anti-tumor effects against Meth A sarcoma and other transplantable tumors in mice." (PMID 27148266, 2016). "(III) Inflammatory cells in the tumor microenvironment can produce large quantities of angiogenic factors and growth factors such as vascular endothelial growth factor (vEGF), TNF a, IL 8 and bFGF." (PMID 26978404, 2016).
tumor (continued). "Whereas soluble factors as IL-6, TGF-β, and TNF-α are well known to improve tumor and stromal survival, recent findings have shown that chemokines secreted by MM cells, such as CCL25, also play an important role in the recruitment of stromal cells." (PMID 27834810, 2016). "Tumor necrosis factor alpha (TNFα) and interferon gamma (IFNγ) were originally identified to show potent anti-tumor activity and immunomodulatory capability." (PMID 27342639, 2016). "TNF-α and IL-6, expressed in the tumor microenvironment, are important for the development of inflammation-associated intestinal tumorigenesis." (PMID 27679575, 2016). "In the other study, NLRX1 was found to function as a tumor suppressor by regulating TNF induced apoptosis in immortalized cell lines." (PMID 27105514, 2016). "FRα-specific T cells exhibited polyfunctionality in their ability to secrete IFN-γ, TNF-α, and IL-2 upon stimulation with FRα+ tumor cells." (PMID 27439908, 2016). "PEP005 favors neutrophil recruitment and activation via MIP-2/IL-8, TNF and IL-1 and tumor elimination via neutrophil mediated ADCC." (PMID 27618112, 2016). "Recent studies shows that the anti-tumor effects of TNF-α were primarily enhanced by the body’s cellular and humoral immune functions, inhibiting tumor angiogenesis and directly inducing tumor cell apoptosis." (PMID 27881109, 2016). "The TNFα and IFNγ synergism has been reported under many biological conditions including their tumor inhibitory effect." (PMID 27342639, 2016). "Lamina propria macrophages are constantly exposed to microbial products and are a major source of pro-inflammatory cytokines, such as TNF-α and IL-6, in the tumor microenvironment." (PMID 27679575, 2016). "As main components of tumor microenvironment, both mouse and human immune cells efficiently produce TNF-α in low concentration of LPS or chemotherapeutic agents treated condition." (PMID 27556690, 2016). "It is well established that pro-inflammatory cytokines and mediators, including IL-1β, IL-6, TNF-α, iNOS and Cox-2 which acts as tumor promoter is tightly modulated by transcription factor NFκB." (PMID 27563884, 2016). "TNF-α, which expressed by the components of tumor microenvironment, was functionally controlled by other pro-inflammatory cytokines in paracrine manner." (PMID 27556690, 2016). "We show that the mTOR inhibitors suppressed invasion and migration in GBM cells in the presence of TNFα and tumor promoter PMA mediated by reduction of PKC-α activity and downregulation of NFκB." (PMID 26940200, 2016). "TNFα is a powerful anti-tumor cytokine as well as a potent inflammatory cytokine which can induce complex immune responses." (PMID 27342639, 2016). "In our study, we imitate the inflammatory tumor microenvironment by adding TNF-α and IFN-γ into the culture medium of MSCs." (PMID 27191496, 2016). "The effects of LSPS on TNF-α and IL-2 levels in the serum of H22 tumor-bearing mice were investigated." (PMID 27827862, 2016). "Externally applied onto the acupoints, Nidus Vespae is experimentally proven to increase TNF-α and IL-6 secretion of monocytes and the IgG production of B cells and promote the phagocytosis of tumor cells by monocytes, effects similar to the SMS herbal remedy." (PMID 27190532, 2016). "Our findings therefore suggest that it is possible to tailor SMAC mimetics for inhibition of IAP family members cIAP1 and cIAP2, thereby modulating tumor responses to TNF and LT-α." (PMID 27617834, 2016). "Although TNFα shows potent anti-tumor activity and produces impressive results in various animal cancer models, clinical use of TNFα as an anticancer drug is hampered by severe systemic toxicity." (PMID 27342639, 2016). "Ultimately, combination therapy led to reduced tumor growth, enhanced survival, increased IFNγ, tumor necrosis factor (TNFα), and Granzyme B within CD8+ T cells further supporting a mechanism of action non-redundant to established NCR blockade in clinic." (PMID 28031817, 2016).